CXCR4 (C-X-C motif chemokine receptor 4)
Diseases named in the same sentence as CXCR4 in open-access papers (continued):
Sharing a sentence is not in itself a finding about the gene and the disease.
pancreatic cancer (continued). "The purpose of this study was to examine the functional role of CXCR4 in the progression of pancreatic cancers and explore the possible mechanism." (PMID 19002187, 2008). "Recently it was shown that the CD133+ CXCR4+ pancreatic CSC population is the only cell population responsible for tumor metastasis in pancreatic cancer." (PMID 18728788, 2008). "Given the important role that CXCR4 plays in the process of pancreatic cancer progression, CXCR4 is a very intriguing therapeutic target." (PMID 19002187, 2008). "With the CXCR4 knockdown, cell growth, cell cycle and cell colony formation ability were inhibited, so pancreatic cancer cell tumorigenesis was prevented effectively." (PMID 19002187, 2008). "The microarray results showed that pancreatic juice from pancreatic cancer patients contained increased RNA level of the CXCR4 gene." (PMID 19002187, 2008). "shRNA against CXCR4 was applied to disrupt the SDF-1/CXCR4 signal transduction pathways in pancreatic cancer cell lines." (PMID 19002187, 2008). "Understanding the precise mechanisms of CXCR4 function should provide insight into attractive pancreatic cancer therapy." (PMID 19002187, 2008). "While CXCL12 mRNA is expressed in pancreatic cancer tissues, CXCR4 mRNA is expressed both in pancreatic cancer tissues and in pancreatic cancer cell lines (AsPC-1, BxPC-3, CFPAC-1, HPAC and PANC-1)." (PMID 19787093, 2008). "Involvement of SDF-1/CXCR4 was reported during prostate cancer, ovarian cancer, colorectal cancer, hepatocellular carcinoma as well as pancreatic cancer." (PMID 19002187, 2008). "Interestingly, among the CXCR4+ cancer types there are solid tumors of high prevalence and very poor response to current treatments such as pancreatic cancer, gastric carcinoma and non-small cell lung cancer." (PMID 40307933, 2025). "The C-X-C motif chemokine receptor 4 (CXCR4) in class A is highly expressed in various cancers, including breast, lung and pancreatic cancer and facilitates metastasis through its ligand C-X-C motif chemokine (CXCL12) (Stromal cell-Derived Factor 1-alpha (SDF-1α))." (PMID 40994571, 2025). "Their findings showed that the T2 enhancement ratio and ΔR2 values could semi-quantitatively assess CXCR4 expression in four pancreatic cancer cell lines (AsPC-1, BxPC-3, CFPAC-1, and PANC-1), potentially serving as prognostic indicators." (PMID 40284444, 2025). "Recent research has revealed that the oral microbiota P. gingivalis can translocate to the pancreas and upregulate the expression of CXCR4 (C-X-C chemokine receptor type 4) in pancreatic cancer cells, a chemokine receptor capable of binding to the fimbriae of P. gingivalis." (PMID 39966840, 2025). "In lung cancer, CXCR4 plays a key role in the spread of metastatic cells to the lymph nodes, while in pancreatic cancer, CXCR4 and CXCR2 are involved in mediating tumor-induced inflammation, which creates a favorable microenvironment for tumor cell survival and spread." (PMID 41024311, 2025). "The over-expression of CXCR4 could promote the migration of pancreatic cancer cell in vitro and in vivo." (PMID 38983932, 2024). "Therefore, the experimental results suggest that CXCR4 can promote the metastasis of pancreatic cancer in vivo and in vitro." (PMID 38983932, 2024). "When CTCs fall from pancreatic cancers into the liver, HM-CTCs (CXCR4+CTC) may directly colonize the liver to metastasize." (PMID 38983932, 2024). "We focused on the CXCR4 gene which was over-expressed in pancreatic cancer." (PMID 38983932, 2024). "CXCR4-targeted tumor therapy has promising applications in pancreatic cancer." (PMID 38983932, 2024). "Herein, we verified the function of CXCR4 gene in vitro and in vivo, which could promote the pancreatic cancer liver metastasis." (PMID 38983932, 2024). "Previous studies have reported that CXCR4 gene can promote the progression of pancreatic cancer." (PMID 38983932, 2024).
pancreatic cancer (continued). "In conclusion, our study observed that CXCR4 could promote the migration of pancreatic cancer in vitro and in vivo." (PMID 38983932, 2024). "A unique anti-PD-L1/CXCR4 bispecific nanobody could successfully penetrate the tumor tissues in a xenograft mouse model and inhibit the growth of pancreatic cancer cells much better than the combination therapy using anti-PD-L1 and anti-CXCR4 nanobodies." (PMID 36761751, 2023). "Pancreatic cancer cells incubated with a conditioned medium from exendin-4-treated stellate cells have a decreased ability to proliferate, migrate, and invade in vitro, similar to effects induced by CXCR4 inhibitor AMD3100." (PMID 37046676, 2023). "The interaction of CXCR4, which is strongly upregulated in various malignancies, with uPAR-associated proteins drives disseminating cells toward metastatic sites, and the complexing of uPA with uPAR regulates EMT to promote pancreatic cancer progression." (PMID 37895906, 2023). "Moreover, a novel CXCR4 antagonist, BL-8040 or motixafortide, in combination with immuno- and chemotherapy, increased anti-tumor immune responses in pancreatic cancer patients." (PMID 36725964, 2023). "We conducted a scientific literature search on Pubmed and Google Scholar including retrospective, prospective studies and reviews focused on the current research elucidating the emerging role of CXCL12 and its receptors CXCR4 – CXCR7 in the pathogenesis of pancreatic cancer." (PMID 37035150, 2023). "A phase II trial suggested that CXCR4 inhibition combined with pembrolizumab can reduce populations of immunosuppressive cells in the tumor microenvironment of patients with chemotherapy-resistant advanced pancreatic cancer." (PMID 36143975, 2022). "The immunosuppressive axis driven by CAFs in a CXCL12-CXCR4-dependent manner is also targeted by the CXCR4 antagonist motixafortide (BL-8040) in combination with anti-PD-1 antibodies in phase II clinical trial for patients with pancreatic cancer (NCT02826486)." (PMID 36338519, 2022). "Interestingly, CXCR4 was found to be expressed at a higher level in pancreatic cancer cell lines derived from metastatic lesions compared to cell lines derived from primary tumors." (PMID 35454943, 2022). "A CXCR4 antagonist (BL-8040) combined with pembrolizumab and chemotherapy can increase the disease control rate of pancreatic cancer patients, promote the tumour infiltration of CD8+ T cells, and decrease the levels of myeloid-derived suppressor cells and circulating regulatory T cells." (PMID 35468838, 2022). "The authors did not look for RON expression or activation status in the studied cell lines, but we may speculate that a dual RON/CXCR4 inhibition might improve metastatic spreading in pancreatic cancer patients." (PMID 35454943, 2022). "In a human pancreatic cancer xenograft model, the anti-PD-L1/CXCR4 nanobody markedly inhibited tumour growth and was superior to the combo-treatment by anti-PD-L1 nanobody and anti-CXCR4 nanobody or treatment with atezolizumab as a positive control." (PMID 36284271, 2022). "In addition to IL6 and TGFβ, CXCR4-mediated signaling also affects pancreatic cancer treatment significantly." (PMID 35453676, 2022). "Interestingly, CXCR4 has been shown to be a key player in pancreatic cancer progression and metastasis." (PMID 35204820, 2022). "In pancreatic cancer, CXCR4 is a target of miR‐381 and its expression is upregulated." (PMID 35014178, 2022). "Moreover, C-X-C motif chemokine receptors also contribute to Gemcitabine resistance, and combination with a CXCR4 antagonist (AMD3100) or hedgehog inhibitor (GDC-0449) with gemcitabine inhibit the growth of orthotopic pancreatic tumor-bearing mice." (PMID 34930261, 2021). "In addition, SDF-1/CXCR4 axis plays a pivotal role in growth, progression and metastasis modulation in diverse kinds of cancers including head and neck cancer, pancreatic cancer and lung cancer." (PMID 33838662, 2021).
pancreatic cancer (continued). "The combined blockage of CXCR4 and PD-1 has also been shown to lead to an increased migration of T cells from the stroma into cancer-cell-rich regions in in vitro organotypic models of pancreatic cancer." (PMID 34203869, 2021). "In pancreatic cancer, where CXCR4 and CXCR7 receptors are commonly co-expressed on tumor cells, blocking or depleting CXCL12 may be a more effective strategy." (PMID 35008248, 2021). "Use of the CXCR4 inhibitor plerixafor was shown to be well tolerated in multiple myeloma patients and in metastatic colorectal and pancreatic cancer patients where it resulted in a tumor cell gene signature suggestive of response to immune-checkpoint mediated therapies." (PMID 33805598, 2021). "Notably, the integrated immune effects of CXCR4 antagonists were also observed in human patients with microsatellite stable colorectal and pancreatic tumors treated with 1 week of continuous infusion of AMD3100." (PMID 34575965, 2021). "The reason for CXCR4 downregulation in pancreatic cancer is unclear." (PMID 34901003, 2021). "Pertinently, there are active trials testing this strategy in metastatic pancreatic cancer patients using BL-8040 (motixafortide), a short synthetic peptide antagonist of CXCR4, in combination with pembrolizumab (NCT02907099) or chemotherapy (NCT02826486 and NCT03193190)." (PMID 35008248, 2021). "Transcriptional analyses of these paired biopsies of metastases from microsatellite stable colorectal cancer and pancreatic cancer showed that CXCR4 inhibition induced an integrated immune response involving multiple mediators of innate and adaptive immune responses." (PMID 35008248, 2021). "It was reported that CQ could decrease pancreatic cancer stem cells via inhibition of CXCL12/CXCR4 signaling." (PMID 34733155, 2021). "Therefore, we performed the further mechanism study in present study, and the results showed that downregulation of c-Myc enhanced the antitumor activity of bufalin on pancreatic cancer cells by suppressing the HIF-1α/SDF-1/CXCR4 pathway." (PMID 32362830, 2020). "Previous studies have shown SDF-1/CXCR4 signaling induces pancreatic cancer cell invasion and EMT." (PMID 32362830, 2020). "Targeting stroma in a murine model of metastatic pancreatic cancer using the immune modulating effect of hyaluronan degradation by PEGPH20 significantly decreased the immunosuppressive effect of CXCL12/CXCR4/CCR7 signaling axis in CAFs, myeloid, and CD8+ T cells." (PMID 32466266, 2020). "Recent studies have verified that SDF-1/CXCR4 signaling could induce pancreatic cancer cell invasion and EMT in vitro." (PMID 32362830, 2020). "Indeed, CXCR4 inhibition yields increased infiltration of T cells into tumors and tumor regression in an in vivo pancreatic cancer mouse model." (PMID 32219196, 2020). "It was proven that the peripheral trafficking of CXCR4+/CD34+/CD133+ VSELs was increased in gastric cancer 20 and pancreatic cancer 21, suggesting that CXCR4 may participate in the formation of gastrointestinal cancer." (PMID 33052232, 2020). "Consequently, this alkaloid exhibited anti-metastasis activities via affecting the CXCR4 and MMPs levels in human lung, prostate, and pancreatic cancer cells." (PMID 32630806, 2020). "Consistently, ARTN and CXC chemokine receptor 4 (CXCR4) were found to be overexpressed in pancreatic cancer tissues, and the migration and invasion of pancreatic cancer cells appears to be promoted by Akt and ERK 1/2/NF‐κB signalling and the stromal cell‐derived factor 1α (SDF‐1α)/CXCR4 axis." (PMID 32573073, 2020). "CXCR4 is demethylated and overexpresed in CAFs and increases pancreatic cancer invasiveness." (PMID 31663852, 2019). "Consequently, blocking the CXCL12/CXCR4 axis improved immuno-oncological approaches such as checkpoint inhibition in models of pancreatic cancer and hepatocellular cancer." (PMID 30813533, 2019).
pancreatic cancer (continued). "Our studies support the use of agents that disrupt the cross talk between malignant cells and the stroma and suggest that CXCR4 inhibitors may have a potential therapeutic role in pancreatic cancer that should be tested in future studies." (PMID 31663852, 2019). "Indeed, both pancreatic cancer cells and tissues highly expressed CXCR4 and ACKR3 receptors on their surface, which are activated by CAFs-released CXCL12 chemokine." (PMID 31275385, 2019). "Our recent studies have shown that exogenous SDF-1 could increase CXCR4-positive pancreatic cancer invasion and EMT, and activated pancreatic cancer stellate cells could secrete SDF-1 and IL-6 to induce EMT in pancreatic cancer." (PMID 30800209, 2019). "TIMP-1-induced production of SDF-1 in the liver could potentially represent one mechanism directing the organotropic metastasis of pancreatic cancer cells, which also express high levels of CXCR4." (PMID 29903049, 2018). "Increased expression of CXCR4 in HT-29/EGFP/FUR cells is in conformity with published data proving that CD133+CXCR4+ cancer stem cells were necessary for tumor metastasis in pancreatic cancer as well as CXCR4 role in oxaliplatin-resistant colorectal cancer cells." (PMID 30143021, 2018). "Taken together, our present work provides solid evidence for reciprocal interactions between CAFs and pancreatic cancer cells, shedding new light on the utilization of the SDF-1/CXCR4/SATB-1 axis as a potential therapeutic target for the treatment of pancreatic cancer." (PMID 30337520, 2018). "In summary, these findings demonstrated that the SDF-1/CXCR4/SATB-1 axis may be a potential new target of clinical interventions for pancreatic cancer patients." (PMID 30337520, 2018). "A number of studies are underway assessing the safety and efficacy of CXCR4 antagonists in patients with solid tumors, such as glioblastoma multiforme, and cancers of the pancreas, ovaries, and colon (ClinicalTrials.gov identifiers NCT02179970, NCT02737072, NCT02765165)." (PMID 29088715, 2017). "Finally, nine studies that were published between 2000 and 2013 were eligible for our meta-analysis that aimed to elucidate the impact of CXCR4 as a prognostic and clinicopathological biomarker in pancreatic cancer." (PMID 26091099, 2015). "Our findings suggested that blocking the PSC-PCC interaction by inhibiting the SDF-1α/CXCR4 signaling pathways may be a promising therapeutic strategy for overcoming chemoresistance in pancreatic cancer." (PMID 25609203, 2015). "Certainly, conditioned medium of PSC increased pancreatic cancer cell proliferation and this effect could be partially inhibited by a CXCR4 inhibitor." (PMID 26010611, 2015). "Our findings indicate that blocking the PSC-PCC interaction by inhibiting SDF-1α/CXCR4 signaling may be a promising therapeutic strategy for overcoming chemoresistance in pancreatic cancer." (PMID 25609203, 2015). "Moreover, it has also been reported that CXCR4 expression is higher in pancreatic cancer cells derived from metastatic lesions compared with those derived from primary tumors." (PMID 25679210, 2015). "Also, downregulation of CXCR4 has been demonstrated in pancreatic cancer cell and CD34+ cells of patients with primary myelofibrosis due to promoter hypermethylation." (PMID 25114911, 2014). "Butein suppressed invasion and CXCR4 expression in breast and pancreatic cancer cells." (PMID 23840271, 2013). "In the same way, the expression levels of CD133, CXCR4 and HIF-1α were also enhanced in the pancreatic cancer cell lines under hypoxia as compared with normoxic conditions and associated with an enhanced invasiveness of CD133+ pancreatic cancer cells." (PMID 23301832, 2013). "Our previous investigations have implicated chemokine receptor CXCR4 and its selective ligand CXCL12 in the pathogenesis and progression of pancreatic intraepithelial neoplasia and invasive pancreatic cancer; hence, CXCR4 is a promising target for suppression of pancreatic cancer growth." (PMID 22319600, 2012).
pancreatic cancer (continued). "Hence our study suggests that efforts to therapeutically target CXCL12 signaling in pancreatic cancer should be focused at the level of the ligand to account for both CXCR4 and CXCR7 activity." (PMID 22472349, 2012). "In contrast to pancreatic cancer stem cells in which CD133+/CXCR4− cells are just as tumorigenic as CD133+/CXCR4+ cells, in prostate tumor initiating cells CXCR4 expression results in significantly greater colony formation and inhibition of CXCR4 with an antagonistic antibody reduces tumor growth." (PMID 22359577, 2012). "Using a cross-disciplinary approach starting with computational modeling of the CXCR4 receptor structure to in vitro analysis of CXCR4 signaling, our study has determined that chloroquine and hydroxychloroquine act as novel CXCR4 inhibitors in pancreatic cancer cells." (PMID 22319600, 2012). "Positive expression of CXCR4 was also detected in the vascular endothelial cells of the pancreas, the peripancreatic lymph nodes, the peripancreatic neural tissue and an ‘island’ of pancreatic cancer." (PMID 23181100, 2012). "In this interdisciplinary investigation, we combined in silico modeling of CXCR4 structure with high-throughput screening and in vitro assays in pancreatic cancer cell lines to identify novel antagonists to CXCR4-mediated cell proliferation in pancreatic cancer cells." (PMID 22319600, 2012). "Therefore, in our study, we evaluated the expression of CXCL12/CXCR4 and found a critical relationship between CXCL12/CXCR4 and tumor stage and grade in pancreatic cancer." (PMID 23181100, 2012). "This hypothesis is supported by findings that the expression pattern of CXCL12 and CXCR4 in pancreatic cancer tissue significantly correlated to clinicopathological features." (PMID 23181100, 2012). "We previously observed CXCR4-mediated increases in cell proliferation in pancreatic cancer cells." (PMID 22319600, 2012). "CXCR4 was expressed in 80.0% of pancreatic carcinoma samples but only 26.7% of normal samples." (PMID 23181100, 2012). "Additionally, in melanoma and pancreatic cancer, the CXCR4 promoter is regulated by increased DNA methylation, which results in lower CXCR4 mRNA expression." (PMID 22220212, 2011). "In addition, they identified a subpopulation of CD133+CXCR4+ pancreatic cancer cells from human pancreatic cancer tissue samples that localized almost exclusively to the invasive front of the tumor." (PMID 21188169, 2011). "Importantly, in previous studies, a chemokine receptor, CXCR4, was shown to be overexpressed in pancreatic cancer tissues and CSCs and has been shown to potentiate pancreatic cancer growth and invasion." (PMID 21045835, 2010). "Our data show that the induced chemoresistance is partly mediated by the activation of Akt and ERK signalling pathways and a small-molecule antagonist against CXCR4 can effectively abrogate the survival signals and resensitise the pancreatic cancer cells to gemcitabine cytotoxicity." (PMID 21045835, 2010). "Importantly, a recent study also showed that a distinct subpopulation of CD133+;CXCR4+ cancer stem cells (CSCs) was present at the leading edge of invasive pancreatic tumours, indicating a potential role of CXCR4 in the invasion process." (PMID 21045835, 2010). "To determine whether the effect of CXCR4 shRNA on metastasis was related to pancreatic cancer in vitro, we conducted the Matrigel chamber invasion assay." (PMID 19002187, 2008). "Moreover, CXCR4 expression was highly expressed in pancreatic cancer cell lines, especially Miapaca-2." (PMID 19002187, 2008). "Collectively, these data reported here demonstrate CXCR4 could modulate the canonical Wnt pathway and perhaps be a promising therapeutic target for pancreatic cancer progression." (PMID 19002187, 2008). "Thus, it suggests that the interaction between CXCL12 and CXCR4 is relevant to pancreatic cancer cell progression and metastasis." (PMID 19787093, 2008).